IDO1 (indoleamine 2,3-dioxygenase 1)
Diseases named in the same sentence as IDO1 in open-access papers (continued):
Sharing a sentence is not in itself a finding about the gene and the disease.
ovarian carcinoma (continued). "Next, we developed a mouse orthotopic model of ovarian cancer to investigate the potential therapeutic value of IDO1.Two weeks after OC orthotopic implantation, the mice were treated with or without 1- Methyl-DL-tryptophan for 6 weeks." (PMID 38468343, 2024). "Among them, 39 genes including IDO1 were closely related to tryptophan metabolism of OC in the TCGA ovarian cancer cohort, and 34 genes, including IDO1, were cohesively associated with tryptophan metabolism of OC in the GSE140082 cohort." (PMID 38468343, 2024). "It has also been widely indicated that IDO1, the first rate-limiting enzyme in the tryptophan-kynurenine (Trp-kyn) metabolism pathway, is upregulated in various cancer tissues, including ovarian cancer, and is related to poor patient prognosis." (PMID 38468343, 2024). "IDO1 is also reported to promote PD-L1 expression in ovarian cancer cells in an AhR-dependent manner." (PMID 38451784, 2024). "This is consistent with our in vitro observations that knockdown of IDO1 alone was insufficient to reduce tumor cell growth in an ovarian cancer model." (PMID 38451784, 2024). "Despite unaltered plasma Kyn levels in ovarian cancer patients, the clear correlation between Kyn/Trp ratios in the plasma and ascites samples suggests that IDO1 and/or TDO activity is responsible for the metabolic changes in both fluids." (PMID 36765849, 2023). "High intratumoral IDO1 expression is correlated with poor prognosis in melanoma, ovarian cancer, colorectal cancer, and lung cancers." (PMID 37114134, 2023). "For this reason, IDO1 expression and activity has been evaluated in countless human cancer types, including ovarian cancer." (PMID 36765849, 2023). "This lack of activity was evidenced in two phase II studies in patients with myelodysplastic syndrome or advanced ovarian cancer, leading to the development of IDO1 inhibitors combined with conventional anticancer medications." (PMID 35173722, 2022). "DDP treatment resulted in S, G2/M cell-cycle arrest in ovarian cancer cells, and here silencing IDO1 arrested more cells in G0/G1 and S phases." (PMID 36233312, 2022). "Here, approximately 51.5% of ovarian cancer patients had high expression of IDO1 in cancer tissues, and a low expression level indicated longer PFS and PFI in type II cancer, which was in agreement with the findings of Taka et el." (PMID 36233312, 2022). "For instance, when exposed to IDO1 inhibitors, ovarian cancer cells develop a metabolic adaptation that switches tryptophan catabolism to the 5-hydroxytryptamine pathway." (PMID 36311734, 2022). "Here, the expression level of IDO1 in tumors in platinum-resistant (n = 22) and -sensitive (n = 46) ovarian cancer patients was determined, and then how IDO1 modulated DDP resistance was explored in vitro and in vivo." (PMID 36233312, 2022). "Preclinical data demonstrated that IDO1 strengthened the immune escape of tumors and that targeting IDO1 suppressed tumor growth in ovarian cancer." (PMID 36233312, 2022). "The aim of this study was to explore the role of IDO1 in the antitumor efficacy of DDP in epithelial ovarian cancer." (PMID 36233312, 2022). "The immunoregulatory enzyme, indoleamine 2,3-dioxygenase (IDO1) and the PD-1/PD-L1 axis are potent mechanisms that impede effective anti-tumor immunity in ovarian cancer." (PMID 34025677, 2021). "Preclinical research showed that IDO1 inhibition by 1-MT also counteracts the invasion of carboplatin-resistant ovarian cancer cells via the down-regulation of IDO expression and re-activation of immune cell function." (PMID 34201791, 2021).
ovarian carcinoma (continued). "Altogether, the impact of tumoral IDO1 expression in ovarian cancer was not only confined to the kynurenine pathway, but also affected nicotinamide, purine and pyrimidine metabolic pathways, and the magnitude of change was influenced by the tumor burden." (PMID 34025677, 2021). "Most studies indicate that IDO1 is correlated with poor prognosis in various cancer types, such as ovarian cancer, esophageal cancer, and penile squamous cell carcinoma." (PMID 34733885, 2021). "Overexpression of IDO1 in various cancer types (including liver, colorectal, breast, and ovarian cancer) has been demonstrated." (PMID 34769098, 2021). "In ovarian cancer, IDO1 has been related to disease progression, chemotherapy resistance and impaired survival, based on expression analysis of IDO1 by in situ hybridization and immunohistochemistry of tumor specimens." (PMID 33584686, 2020). "Unexpectedly, in an IDO1 positive ovarian cancer cell line, Indoximod triggered an increased IFNγ-induced release of the TRP metabolite KYN concurrent with an increase of IDO1 mRNA indicating an activation of KP instead of anticipated inhibition." (PMID 31417567, 2019). "The expression of IDO1 in cervical cancer, breast cancer, ovarian cancer, endometrial cancer, colon cancer, and brain tumors predicts less satisfied clinical prognosis." (PMID 30314496, 2018). "Here we used an ovarian cancer cell line SKOV-3 that endogenously expresses IDO1 upon IFNγ treatment to develop functional assays for screening IDO1 inhibitors." (PMID 30112109, 2018). "Additionally, the authors showed that the combination of the IDO1 inhibitor epacadostat and a purinergic receptor antagonist was able to rescue T cell function and proliferation in mouse models for ovarian cancer." (PMID 39272943, 2024). "As expected, IDO1 was highly upregulated in ovarian cancer cell lines." (PMID 38468343, 2024). "Based on this recent evidence, IDO1 plasticity was investigated in the human ovarian cancer cell line, SKOV-3, that constitutively expresses IDO1 in a dynamic balance between the holo- and apo-protein, and thus potentially endowed with a dual function (i.e., enzymatic and non-enzymatic)." (PMID 38333210, 2024). "Indeed, IDO1-overexpression ovarian cancer cell-derived EVs decreased the endothelial ATP content while IDO1-knockdown ovarian cancer cell-derived EVs increased the endothelial ATP content." (PMID 38468343, 2024). "High IDO1 expression corresponds with higher survival in ovarian cancer." (PMID 39672307, 2024). "To further clarify the molecular mechanisms by how IDO1high ovarian cancer cell-derived EVs promote endothelial mitophagy, we first detected L-kyn levels in the culture supernatant and in EVs obtained from IDO1-overexpression and -knockdown ovarian cancer cells using ELISA assay." (PMID 38468343, 2024). "Collectively, this evidence indicated that IDO1 high ovarian cancer cells could deliver L-kyn to endothelial cells through EVs." (PMID 38468343, 2024). "Additionally, we detected the mRNA and protein expression level of IDO1 in common ovarian cancer cell lines (A2780, SKOV3) and normal ovarian cell line using qRT-PCR and Western blot." (PMID 38468343, 2024). "In summary, we observed that IDO1 transcript expression varies substantially between and within cancer types, with uterine and ovarian cancers having the highest proportion of high expressors and hepatobiliary cancers having no high expressors, albeit with a limited number of patients tested." (PMID 38632994, 2024). "Additionally, these IDO1-overexpression ovarian cancer cell-derived EVs were also found to enhance endothelial IDO1expression, in contrast to EVs from IDO1-knockdown or -control ovarian cancer cells." (PMID 38468343, 2024). "We also observed that ovarian cancer cells are more dependent on TDO2 than IDO1, which could further explain why single targeting of IDO1 has been clinically insufficient." (PMID 38451784, 2024).
ovarian carcinoma (continued). "Thus, we assessed L-kyn level in the endothelial cells after cotreatment with EVs acquired from IDO1-overexpression ovarian cancer cells." (PMID 38468343, 2024). "IDO1 has now been shown to be highly expressed in ovarian cancer, which is strongly correlated with the infiltration of immune cell populations, especially dendritic cells and T cells, being an important immune-related gene in ovarian cancer." (PMID 39253578, 2024). "Our analysis of the DepMap database revealed that low micromolar concentrations of epacadostat increased the growth of most ovarian cancer cell lines, providing additional confirmation that IDO1 inhibition alone is insufficient to reduce tumor cell growth without corresponding targeting of TDO2." (PMID 38451784, 2024). "Whereas no indication was found for enhanced l-arginine or l-glutamine metabolism by immunosuppressive enzymes in ovarian cancer patients, metabolism of l-tryptophan by indoleamine 2,3-dioxygenase 1 (IDO1) was significantly elevated compared to healthy controls." (PMID 36765849, 2023). "Hence, it is important to further investigate the role of arginine transport and IDO1 in the development of platinum resistance in ovarian cancer cells." (PMID 37681030, 2023). "In ovarian cancer, high IDO1 expression also correlates with increased drug resistance." (PMID 37114134, 2023). "In addition, in ovarian cancers, they are essential for immunosuppression due to their expression of indoleamine 2,3-dioxygenase 1 (IDO1) and the inducible T cell costimulatory ligand (ICOSL)." (PMID 36982677, 2023). "In addition, IDO1 is a significant immune-related gene in female cancers, and the high expression of IDO1 is connected with good prognosis in breast and ovarian cancer." (PMID 36726489, 2023). "Notably, metabolite levels associated with IDO1 and IL4I1 activity were elevated in ovarian cancer ascites compared to plasma samples." (PMID 36765849, 2023). "Indoleamine 2,3-dioxygenase 1 (IDO1) is a heme-containing dioxygenase that may play a part in chemoresistance in ovarian cancer." (PMID 36233312, 2022). "In addition, the expression of IDO1 in the tumor microenvironnement of ovarian cancer promoted PD-1 expression in T cells via AhR activation." (PMID 35173722, 2022). "Therefore, IDO1 was a determinant for the therapeutic outcome in ovarian cancer patients receiving platinum-based chemotherapy." (PMID 36233312, 2022). "However, the relationship between IDO1 expression and the cellular response to DDP in ovarian cancer, and the underlying molecular mechanisms have been limitedly understood." (PMID 36233312, 2022). "Furthermore, pDCs occur in ovarian cancers, where they are essential for immunosuppression through their expression of indoleamine 2,3-dioxygenase 1 (IDO1) and inducible T cell costimulatory ligand (ICOSL)." (PMID 35267487, 2022). "The results showed that they could better predict the sensitivity of ovarian cancer patients to chemotherapeutic drugs than which based on single gene like IDO1, PI3 and TRIM22." (PMID 34736480, 2021). "Finally, we studied the expression and activity of IDO1 in primary cell cultures established from the malignant ascites of ovarian cancer patients." (PMID 33584686, 2020). "Importantly, GA-NPs@DCV exerts potent anti-ovarian cancer effects by promoting immune activation, inhibiting immune evasion through the Stat3/IDO1/AhR signaling axis, and remodeling tumor immune microenvironment via regulation of the tryptophan metabolic pathway." (PMID 41743162, 2026). "Spatial proteogenomic profiling in ovarian cancer supports these single-cell inferences: immune-excluded regions are enriched for Tregs and fibronectin-rich stroma, whereas diffuse, tumor-proximal immune niches exhibit higher PD-L1/IDO1 and activated lymphocyte markers." (PMID 41181126, 2025).
ovarian carcinoma (continued). "In this study, using preclinical models and clinical specimens, we determine that targeting TRP metabolism via a dual TDO2/IDO1 inhibitor reduces protumor intrinsic cell phenotypes as well as immunosuppressive markers in macrophages, which could be clinically impactful in ovarian cancer." (PMID 38451784, 2024). "Therefore, inhibition of IDO1 activity may enhance the sensitivity of OvCa cells to chemotherapy agents and may serve as a potential target for anti-ovarian cancer therapy." (PMID 37256178, 2023). "Therefore, MRPL15 may lead to immune tolerance of ovarian cancer by participating in the downstream mTOR pathway of IDO1, thereby promoting the progression of ovarian cancer." (PMID 33934540, 2021). "IDO1 inhibition enhanced T-cell proliferation via AKT signaling, restored T-cell cytotoxicity, and increased ovarian cancer cell apoptosis." (PMID 41078340, 2025). "In the human ovarian cancer cell line SKOV-3, IDO1 is endogenously expressed in a dynamical balance between the holo- and the apo-conformation, depending on the intracellular heme availability and factors stabilizing the protein conformation." (PMID 38333210, 2024). "In the current study, we compared proliferation following the genetic knockdown of IDO1, TDO2, and AhR in ovarian cancer cell lines and observed a more robust antiproliferation response in the setting of TDO2 knockdown." (PMID 38451784, 2024). "Although TDO2 mRNA and proteins are higher than those of IDO1 in TNBC, both enzymes can be expressed, and we find this to be the case in ovarian cancer as well." (PMID 39311710, 2024). "Western blot revealed that IDO1high ovarian cancer cell-derived EVs upregulated the LC3II/LC3I ratio and IDO1 expression in endothelial cells." (PMID 38468343, 2024). "To investigate the relative contributions of IDO1 versus TDO2, we generated shRNA-mediated knockdown IDO1 and TDO2, as well as the downstream KYN receptor AhR in human ovarian cancer OVCAR3 cells." (PMID 38451784, 2024). "At baseline disease, we found that the activity of IDO1 was increased in ovarian cancer patients compared to healthy controls, whereas elevated activity of IL4I1 was also found in ovarian cancer ascites samples." (PMID 36765849, 2023). "Therefore, IDO1 may impact on the action of DDP through the ROS pathway in ovarian cancer." (PMID 36233312, 2022). "Previous studies have demonstrated that IDO1, ARG1 and iNOS are expressed in various types of cells in the ovarian cancer ascites." (PMID 32208517, 2020). "SKOV-3 ovarian carcinoma and NCI-H596 adeno-squamous lung cancer cells expressed IDO1 mRNA and IDO protein and constitutively released kynurenine into the supernatant." (PMID 24657910, 2014). "Interestingly, an overlapping effect was observed in the human ovarian cancer cell line SKOV-3, where EPA, LIN, and NAV also prolonged the half-life of the IDO1 protein while simultaneously inhibiting its catalytic activity." (PMID 41262240, 2025). "In ovarian cancer, the IDO1 inhibitor epacadostat demonstrated no significant advantage over tamoxifen in a phase II clinical trial; however, the drug was well tolerated." (PMID 38451784, 2024). "In addition to IDO1 and IL4I1, enhanced ARG1 expression has previously been reported in the context of human ovarian cancer." (PMID 36765849, 2023). "The elevated activity of both IDO1 and IL4I1 found in ovarian cancer patients therefore supports the hypothesis of IL4I1 as a potential resistance mechanism against IDO1 inhibition." (PMID 36765849, 2023). "In several tumor types, including ECs and ovarian cancers, IDO1 expression can be observed in non-inflamed tumors and is confined to tumor cells themselves." (PMID 36119020, 2022).
ovarian carcinoma (continued). "The present study explored the relationship between IDO1 and the DDP efficacy in ovarian cancer." (PMID 36233312, 2022). "IDO1-expressing plasmacytoid DCs were found in malignant melanoma tumor-draining lymph nodes (TDLNs); IDO-expressing macrophages have also been isolated from human ovarian cancer." (PMID 35681736, 2022). "And it indicated that single gene expression of IDO1, PI3 and TRIM22 could influence the chemotherapy sensitivity of ovarian cancer patients." (PMID 34736480, 2021). "Additionally, MRPL15 showed the lowest expression in C3 ovarian cancer and was correlated with proliferation of CD8+ T cells and dendritic cells as well as TGFβR1 and IDO1 expression." (PMID 33934540, 2021). "Finally, we studied the expression of IDO1 and its modulation by NTRC 3883-0 in ex vivo primary cell cultures established from the malignant ascites of ovarian cancer patients." (PMID 33584686, 2020). "Moreover, we compared the expression levels of IDO1 between OC tissues and non-OC tissues using the TCGA ovarian cancer cohort, the previous RNA-seq dataset (GSE140082) and GETx." (PMID 38468343, 2024). "Second, the impact of tumoral IDO1 expression in ovarian cancer was not confined to the kynurenine pathway, but also mediated metabolic changes downstream of kynurenine, demonstrating a role for nicotinate, nicotinamide, purine and pyrimidine metabolic pathways." (PMID 34025677, 2021). "Notably, our study found that crucial immune repressive receptors—which have gained significant attention in ovarian cancer research, such as TIM3, CSF1R, CTLA4, PD1, and LAG3 as well as inhibitory enzymes such as IDO1—were closely related to ALOX5AP expression." (PMID 34094977, 2021). "Despite the bulk of evidence supporting a role for IDO1 in promoting tumor formation and tumor immune escape, there have been clinical studies showing an anti-tumor effect of IDO1 by the intermediate of IFN-γ, which was effective in the therapy of ovarian carcinoma and bladder cancer." (PMID 34943977, 2021). "Our studies with primary ovarian cancer cell cultures isolated from ascites indicate that determination of basal IDO1 gene expression may not be sufficient." (PMID 33584686, 2020). "Thus, the scoring model based on the gene expressions of CXCL13, IDO1, PI3, SPP1 and TRIM22 from GSE15622 dataset and constructed by lasso algorithm could better predict the sensitivity of ovarian cancer patients to chemotherapeutic drugs than which based on single gene." (PMID 34736480, 2021). "Notably, the prevailing metabolic profile of ovarian cancer patients was characterized by an apparent lack of elevated IL4I1 activity on Trp, the common substrate of IDO1, TDO and IL4I1." (PMID 36765849, 2023).